RN7SL155P (RNA, 7SL, cytoplasmic 155, pseudogene)
Gene: Miscellaneous RNA gene on chromosome 19 (18,631,646 to 18,631,908, reverse strand). Ensembl gene ENSG00000263490.
Homologues: Paralogues in human: Metazoa_SRP (85% identical), RN7SL202P (79% identical), RN7SL279P (78% identical), Metazoa_SRP (77% identical), Metazoa_SRP (76% identical), RN7SL48P (76% identical), RN7SL377P (76% identical), RN7SL716P (76% identical), Metazoa_SRP (75% identical), RN7SL850P (75% identical), Metazoa_SRP (74% identical), RN7SL32P (74% identical), and 700 more.